TLR4 (toll like receptor 4)
Diseases named in the same sentence as TLR4 in open-access papers (continued):
Sharing a sentence is not in itself a finding about the gene and the disease.
tumor (continued). "TAK-242 was also used to demonstrate that PC activate healthy MSC in pro-tumor stromal cells through a pro-inflammatory phenotype mediated by TLR4 signaling." (PMID 31541083, 2019). "The importance of TLR4 has been previously shown to enhance tumor survival, chemoresistance and proposed as a novel treatment target in chemoresistant OvCa." (PMID 31652965, 2019). "It has also been reported that CRC cells form mouse models infected by F. nucleatum present increased stimulation of TLR4 that enhances the expression of microRNA-21 (miR-21) ultimately increasing tumor proliferation." (PMID 31450675, 2019). "In this present study, it was found that TLR4 participated in the inhibiting apoptosis effect of POL-P3b on intestinal DC isolated from tumor-burdened mice." (PMID 31277622, 2019). "To better investigate the role of TLR4 in pro-tumor activity of MM-MSC, we used the adult zebrafish as in vivo model of MM engraftment." (PMID 31541083, 2019). "This activated the innate immune response and induced a type I IFN signature in TLR4/MyD88-dependent manner, which stimulated antitumor T cell adaptive immunity and restrained tumor growth." (PMID 31324798, 2019). "TLR4 activation can promote tumor progression by promoting apoptosis resistance, invasion, metastasis, and immune surveillance evasion." (PMID 30636642, 2019). "In TLR4 knockout mice however, the effect of sleep fragmentation on tumor progression was completely abolished." (PMID 31174326, 2019). "The bacterium is also associated with upregulation of several inflammatory cytokines through a postulated miRNA-mediated activation of TLR2/TLR4 and activation of the JAK/STAT and MAPK/ERK pathways linked to CRC tumor progression." (PMID 31367996, 2019). "To further investigate those functions, we evaluated the effect of toll-like receptor 4 (TLR4) activation on the immune modulatory properties of exosomes released by tumor cells." (PMID 31186484, 2019). "It was observed that MIP therapy led to significant tumor regression in wild-type and TLR4−/− mice, compared with PBS-treated control animals." (PMID 31590685, 2019). "Specifically, exosomes produced by tumor cells after TLR4 activation strongly induce the release of pro-inflammatory cytokines and chemokines in monocytes." (PMID 31186484, 2019). "It is believed that the role of TLR4 signaling in tumors is mainly due to the signaling pathway of proinflammatory cytokines (the expression of which is mediated by TLR) to promote the tumor-promoting effect of microenvironment." (PMID 31772935, 2019). "Cai and colleagues evaluated tissue and serum samples from 102 patients and measured the levels of Galectin 3 and toll-like teceptor 4 (TLR4) and attempted to parallel their levels to tumor paclitaxel resistance." (PMID 31652965, 2019). "Alternatively, stimulating TLR2 and TLR4 signaling can promote an anti-tumor immune response in OC models in combination with platinum therapy." (PMID 31443240, 2019). "Nevertheless, more evidence should be obtained to confirm the mechanism underlying TLR4/MD-2 signaling through CXCR7 and the synergistic action of these molecules in tumor development and progression." (PMID 30636642, 2019). "S100A9 secreted from tumor cells is an important regulator of the tumor microenvironment and is an endogenous activator of TLR4." (PMID 31727865, 2019). "Consistently, Tlr4−/− mice also showed reduced tumor reactive T cells and IFNγ production compared with WT mice when vaccinated with the identical dying cells." (PMID 31324798, 2019). "In Kaposi’s sarcoma, known to be induced by herpes 8 virus, marked reduction of TLR2 and TLR4 was found in tumor cells, what resulted in downregulation of pro-inflammatory cytokine response." (PMID 30976817, 2019). "In conclusion, the present study demonstrates that the activation of TLR4 contributes to cancer progression by promoting the release of more effective immunosuppressive exosomes, which allow tumor cells to escape immune surveillance." (PMID 31186484, 2019).
tumor (continued). "To determine the role of TLR4 in MM-MSC tumor-promoting phenotype, we blocked its signaling by addition of TAK-242." (PMID 31541083, 2019). "The effects of Wnt5a on other TLR4-expressing cells of various origin, such as tumor cells expressing TLR4, should however be investigated." (PMID 31098409, 2019). "In this experiments, scientisits found that TLR4 signalling pathway is prerequisite in triggering the anti-tumour immune response and FlaB/TLR5 pathway augment this reaction." (PMID 31528208, 2019). "TLR4 activity in tumor-recruited immune cells promotes immunosuppressive effects by modifying secreted cytokines in the tumor microenvironment and T-cell maturation." (PMID 30774778, 2019). "It is concluded that RPS3 is released from tumor cells when treated with an anticancer drug and that RPS3 can associate with TLR4." (PMID 30819254, 2019). "A high TLR2 and a high TLR4 expression associated with pT2–4 tumours (p = 0.043; p = 0.049), and a high TLR7 expression associated with pT3 tumours (p = 0.025)." (PMID 31467388, 2019). "Further, the role of TLR4 in OS was investigated via subgroup analysis based on the main features, including ethnic lines, tumor type, HR obtain method, analysis type, and cut-off value." (PMID 29560134, 2018). "Studies in which TLR4 is activated by Salmonella choleraesuis revealed less tumor growth in a melanoma murine model, and this decrease was associated to the recruitment of innate immune response cells such as neutrophils and macrophages." (PMID 30302344, 2018). "Inhibition of HMGB1/TLR4 interaction suppressed GC-Ex-induced pro-tumor activation of neutrophils, supporting that HMGB1 is a key factor for the roles of GC-Ex." (PMID 30292233, 2018). "The protective effect role of TLR-4 absence was also confirmed in our clinical study, with notably expression of TLR-4 in human GBM samples, pointing out a critical role of TLR-4 as biomarker of tumor metastasis and prognosis." (PMID 30680070, 2018). "The impact of the TLR4-mediated pathway to control the production of IL-6 and IL-8 has been shown and that after release into the tumor microenvironment, it can have a paracrine effect on either the neighboring cancer cells to survive or resist to PTX." (PMID 29486738, 2018). "TLR4 is the classic receptor of lipopolysaccharides (LPS) and lipid (A), the lipid part of LPS to which the anti-tumor activity of LPS was attributed." (PMID 29983866, 2018). "Tumor cell-released HMGB1 interacts with TLR4 on platelets, mediating the interaction of tumor cells and platelets to promote metastasis." (PMID 29636841, 2018). "On the other hand, tumor-bearing TLR4−/− TB mice presented less adipocyte atrophy and a reduction in the number of TNF-α and CD-68 positive cells in scAT when compared to WT TB group." (PMID 30575787, 2018). "Toll‐like receptor 4 (TLR4) is often overexpressed in malignant and tumour‐infiltrating immune cells." (PMID 29602239, 2018). "Regarding different OC cell lines (OVCAR3, SKOV3, A2780), the TLR4 activation induced IL-1 receptor-associated kinase (IRAK)-4 and NF-kB signaling, and c-Jun, IL-6 and IL-8 production, all of which related to tumor chemoresistance." (PMID 29343281, 2018). "We have identified tumor mutation signatures and associated causal networks in NAFLD-associated HCC in HepPten- mice and further demonstrated the important role of TLR4 in promoting HCC development." (PMID 30034633, 2018). "Taken together, these results suggest that GC-Ex delivers HMGB1 to neutrophils and induces pro-tumor activation through TLR4/NF-κB signaling." (PMID 30292233, 2018). "Blood samples and tumor biopsies from treated and/or abscopal sites were obtained pre- and post-G100 for TLR4 expression by IHC, lymphocyte markers and RNA expression." (PMID 30400835, 2018). "Hsp70 is secreted by adherent tumor cells upon heat shock reaction and acts as a DC antigen, which increases immunity against tumor cells through TLR4 in DCs." (PMID 30227629, 2018).
tumor (continued). "Using TLR4 knockout (TLR4−/−) mice with the MCA205 tumor model confirmed the involvement of TLR4 in S100A4-dependent signaling in vivo." (PMID 29556233, 2018). "Activation of TLR4 in tumor cells promotes the synthesis of NFκB target genes, including IL-6 and IL1β, which results in resistance of tumor cells against cytotoxic lymphocytes." (PMID 29679017, 2018). "A recent report showed that priming of tumor induced macrophages with TLR4 agonist (LPS) alone or in combination with IFN-γ induced a strong anti-tumor immune reaction." (PMID 29983866, 2018). "TLR4 has been previously reported as having high expression in a variety of cancers and was found to be involved in tumor proliferation, immune escape, metastasis and PTX resistance." (PMID 29486738, 2018). "As an immune-activating factor, HMGB1 released from necrotic tumor cells binds to Toll-like receptor 4 (TLR4) expressed by dendritic cells (DCs) to promote antigen presentation and also activates macrophage TNF release and thus activates antitumor immunity." (PMID 30643519, 2018). "Triggering of TLR4 on tumor cells by LPS induces the release of several mediators that can favor tumor cell resistance to cytotoxic lymphocytes, reduces apoptosis, and increases invasiveness." (PMID 29686833, 2018). "When macrophage MGLL was deficient (For example, in tumor microenvironment), increase of 2-AG would activate the CB2-mediated TLR4 suppression, and simultaneously free fatty acid-stimulated TLR4 would also be restricted." (PMID 29968710, 2018). "Comparable to results with S100A4−/− mice, tumors in TLR4−/− mice were significantly smaller than those in WT mice starting at day 17 after tumor-cell inoculation." (PMID 29556233, 2018). "LPS activates TLR4 signaling in tumor cells, leading to tumor evasion from immune surveillance and tumor growth delay." (PMID 30034291, 2018). "And downregulation of TLR4 not only inhibits the tumor growth and cell colony formation in cancers, but also suppresses the metastasis of carcinoma." (PMID 29560134, 2018). "Induced resistance to TNF-related apoptosis-inducing ligand (TRAIL)-induced apoptosis in tumor cells and enhanced secretion of immunosuppressive cytokines have been attributed to TLR4 ligation on tumor cells 42,43." (PMID 30774831, 2018). "Activated macrophages via TLR4-dependent signaling pathways, improved immunity, and inhibited tumor growth." (PMID 30410443, 2018). "The host is primed with four LV305 vaccinations carrying the tumour antigen, alternating with the G305 vaccine-carrying tumour antigen and the TLR4 agonist, glycopyranosyl lipid A, which is a potent dendritic cell activator." (PMID 30577459, 2018). "Immunohistochemical analysis of tumor specimens confirmed significantly lower expression of TLR4 protein in HPV+ tumors compared to HPV– tumors ex-vivo." (PMID 29416610, 2018). "Here, TLR4 expressed on HCC cells mediates the pro-tumor effects and mechanisms of M2-polarized macrophages." (PMID 29338742, 2018). "TLR4 activation in patients with recurrent bacterial infections promotes tumor growth and shields MCL cells from surveillance by the immune system." (PMID 29907126, 2018). "Because of TLR4’s involvement in cancer cell signaling, it is likely that fetuin-A is one of the ligands that signals through TLR4 to drive tumor progression." (PMID 30060600, 2018). "Of note, S100s have also been over-expressed in many inflammation-associated tumors and contributed to disease progression by activating TLR4 or RAGE signal cascades in tumor cells." (PMID 29795379, 2018). "MDSCs isolated from the spleens of tumor-bearing WT mice (positive for S100A4) responded to the TLR4 inhibitor with significantly increased apoptosis compared with that in control MDSCs." (PMID 29556233, 2018). "It was shown that TADCs modified with CD70 and simultaneously activated via CD40 and TLR4, were able to migrate to tumor draining lymph nodes and stimulate tumor-specific CD8+ T cells." (PMID 30233579, 2018).
tumor (continued). "Activating the TLR4 expressed on tumor cells to promote tumor cell survival, and upregulate the expression of nuclear factor-kappa B (NF-κB) and antiapoptotic proteins." (PMID 29560134, 2018). "In terms of chemosensitivity, PAUF and TLR4 expression correlated with chemoresistant tumor (p = 0.017 and p = 0.001, respectively)." (PMID 30111860, 2018). "Treatment with tea polyphenols decreased the tumor size and tumor volume along with the inhibition of TLR4 protein expression as compared with the control group." (PMID 30585192, 2018). "Mice were CO2-euthanized and serum TNF-α level, TLR-2 and TLR-4 expression in peritoneal macrophages and tumor growth measured." (PMID 29588627, 2018). "Few TUNEL-positive apoptotic cells were found in Control WT tumor sections, while TLR-4 absence determined a significant increase in TUNEL positive cells on tumor sections." (PMID 30680070, 2018). "TLR4 was also correlated with tumor development and protection of cancer cells from host immune response in an HNSCC study." (PMID 29854832, 2018). "TLR4 can also enhance tumor cell–platelet interactions, a function that is, at least in part, dependent on the release of endogenous ligand HMGB1 by tumor or damaged cells." (PMID 28894697, 2017). "LPS-triggered TLR4 activation in turn triggers the mitogen-activated protein kinase signaling pathway, which promotes tumor cell proliferation and facilitates inflammation." (PMID 28881826, 2017). "Collectively, these data show that TLR4-induced experimental M-LECP are capable of generating functional lymphatic vessels in vivo as evidenced by increased dissemination of tumor cells to lymph nodes." (PMID 28598999, 2017). "Here, we developed an immunotherapeutic regimen capable of eliminating large established mouse tumors using HMGN1, a DC-activating TLR4 agonist capable of inducing anti-tumor immunity." (PMID 29079801, 2017). "In contrast, free CRT molecules released by tumor cells mainly function as a TLR4 agonist against myeloid cells, leading to inflammatory cytokine production." (PMID 29075268, 2017). "Immunomax, a new defined TLR4 agonist, prolongs the survival of mice following primary 4T1 tumor resection by activating DCs and NK cells co-operation in tumor microenvironment." (PMID 29029545, 2017). "HEK293/TLR4 used in this study was normal human embryonic kidney cells, whereas malignant tumor cells, used by other groups, demonstrated sustained proliferation and high metabolic rate." (PMID 29147073, 2017). "Accumulating evidences demonstrated that the activation of TLR4 in tumor microenvironment can boost the anti-tumor immunity including dendritic cells (DCs) maturation, and antigen presentation." (PMID 29029545, 2017). "This indicates that TLR4 signaling pathway is probably involved in the anti-tumor and immunomodulation effects induced by APS." (PMID 28303957, 2017). "We observed specific phosphorylation changes of pERK and pJNK dependent on the TLR4 levels in tumor keratinocytes." (PMID 28982115, 2017). "We did not detect any significant difference in the staining intensity of CD31 and CD68 in the tumor infiltrate between the TLR4 tumors and control tumors." (PMID 28982115, 2017). "We therefore administered lipopolysaccharide (LPS) as a potent TLR4 agonist subcutaneously in close proximity to the inguinal (draining) lymph nodes (dLN) on days 5 and 9 post-tumour cell injection." (PMID 28924177, 2017). "Immunomax, a plant-derived agonist for TLR4, is currently in preclinical testing in mice for metastatic breast cancer with prolonged survival as well as decreasing tumor development in 31% of mice." (PMID 29190881, 2017). "As a member of pattern recognition receptors, toll-like receptor 4 (TLR4) plays a pivotal role in tumor immune microenvironment and has been increasingly investigated." (PMID 28484456, 2017).
tumor (continued). "SCC13 tumor cells were stably transfected with TLR4 expressing and control plasmid and maintained in culture under selection conditions (Blasticidine, 10μg/ml)." (PMID 28982115, 2017). "In conclusion, the TLR4-mediated MyD88-dependent signaling pathway is probably one of the APS-induced signal pathways underlying the immunoregulation and anti-tumor effects of APS both in vitro and in vivo." (PMID 28303957, 2017). "While, TLR4 expression was reduced significantly by R2016 in both tumor cell types (4x vs. 2x reduction than control in LLC vs. B16F10 cells, respectively)." (PMID 28282460, 2017). "It is demonstrated that irradiated tumor cells released HMGB1 can activate TLR4 on dendritic cells and lead to tumor elimination by tumor-specific T cells." (PMID 28969092, 2017). "PAUF, a soluble protein involved in pancreatic tumorigenesis and metastasis, interacted with TLR4 on the surface of MDSCs and enhanced their immunosuppressive effects on activated T cells in tumor microenvironment." (PMID 29029545, 2017). "TLR4 is activated via Immunomax turning on dendritic cells, eventually triggering tumoricidal natural killer cells to inhibit tumor growth." (PMID 29190881, 2017). "TLR4 expressed on DCs play a role in promoting anti-tumor immune response, but that expressed by MDSCs, vascular epithelial cells, macrophages MSCs and tumor cells play the opposite role." (PMID 29029545, 2017). "Further involvement of TLR4 as a mediator of tumor-promoting oligo-HA signaling was reported for a melanoma tumor model." (PMID 29062810, 2017). "It has been suggested that the ability of taxanes to induce the production of inflammatory cytokines involves the direct activation of TLR4; however, clear evidence for this has yet to be demonstrated in tumor cells." (PMID 28915246, 2017). "Above all, TLR4 expressed on TAMs is one component of mechanisms responsible for the recruitment of macrophages into tumor microenvironment." (PMID 29029545, 2017). "Altogether we assume that TLR4 impacts keratinocyte biology as a regulator of proliferation in normal and tumor keratinocytes and also in the migration of tumor cells." (PMID 28982115, 2017). "Nevertheless, this model highlighted that a tumor specific CTL response can be stimulated along the LPS/ TLR4 axis alone." (PMID 28445131, 2017). "The overexpression of TLR4 in SCC13 tumor cells was followed by phosphorylation of ERK1/2 and JNK and increased expression of ATF3." (PMID 28982115, 2017). "Extracellular HMGB1 can promote NFκB transportation to the nucleus and induce expression of inflammatory factor and tumor cell proliferation via TLR4 signaling pathway." (PMID 28969092, 2017). "In TLR4+/+ tumor-bearing mice, the levels of TNF-α and IL-6 in APS and LPS groups were significantly higher than those in NS and ADM TLR4+/+ groups (P < 0.05)." (PMID 28303957, 2017). "In the context of chemo- or radiotherapy, the expression of TLR4 and activation of MyD88 mainly on dendritic cells were crucial for efficient induction of anti-tumour immunity." (PMID 28300057, 2017). "In summary, TLR4 negatively regulates the proliferation of keratinocytes and its overexpression reduces tumor growth of SCC cells." (PMID 28982115, 2017). "B cell activation is induced by tumor-derived autophagosomes (Dribbles), which sequester various tumor antigens in a TLR4/MYD88-dependent reaction." (PMID 28771183, 2017). "Tumor Necrosis Factor alpha (TNF-α) has been shown to be released by tumor cells in response to docetaxel, and lipopolysaccharides (LPS), the latter through activation of toll-like receptor 4 (TLR4)." (PMID 28915246, 2017). "Human patient material and in vivo models in rodents have been studied for the involvement of TLR4 in tumor progression, although the focus of these projects was mainly on the involvement of the innate immune system." (PMID 28982115, 2017).